MGMT (O-6-methylguanine-DNA methyltransferase)
Diseases named in the same sentence as MGMT in open-access papers (continued):
Sharing a sentence is not in itself a finding about the gene and the disease.
glioblastoma (continued). "We propose that combining the DIAPH3 expression with MGMT methylation could offer a better prediction of survival and more adapted postsurgical treatment for patients with MGMT-methylated glioblastoma." (PMID 38454929, 2024). "Additionally, the use of nanotechnology to target MGMT-mediated resistance in glioblastoma represents an innovative strategy." (PMID 39055560, 2024). "It has been suggested that some patients with MGMT unmethylated glioblastoma may benefit from temozolomide, as observed in various cohorts and large-scale studies; however, this is largely due to testing bias." (PMID 38646145, 2024). "Based on these findings, the authors argued that efforts to reduce thrombocytopenia could improve the exposure to lomustine and thereby clinical outcomes in patients with recurrent glioblastoma and MGMT promoter methylation." (PMID 38571509, 2024). "The MGMT normally protects cells against the damage of alkylating agents such as temozolomide, and therefore its inhibited expression through methylation is related to a better prognosis during standard-of-care chemotherapy for glioblastoma." (PMID 38308012, 2024). "Hence, we proposed a weakly supervised prediction model for MGMT promoter methylation status in glioblastoma based on computational pathology with H&E-stained histopathological slides." (PMID 38385046, 2024). "Interestingly, maintenance of the glioblastoma stem cell state has been found to correlate with MGMT expression." (PMID 38730694, 2024). "Additionally, rapamycin induced the expression of the DNA repair enzyme O-6-methylguanine-DNA methyltransferase (MGMT) in glioblastoma cells with an unmethylated MGMT gene promotor." (PMID 38182566, 2024). "The aim of this study was to retrospectively collect MRI data, and to develop a radiomics model by incorporating imaging features from multiple tumor subregions on multi-sequence MRI to predict preoperative MGMT methylation status in patients with glioblastoma." (PMID 38992201, 2024). "O6-methylguanine-DNA methyltransferase (MGMT) promoter methylation is shown to have survival benefit for glioblastoma patients undergoing maximal safe resection, radiotherapy and concomitant temozolomide (TMZ) followed by 6 cycles of adjuvant TMZ, acting as prognostic marker." (PMID 39367282, 2024). "The effectiveness of PC was noted to be unsatisfactory, with a median OS from PC administration of 9.7 months (95% CI 6.7 to 12.7) and median PFS of 8 weeks, in a South Korean single-arm trial that enrolled eight patients with MGMT-methylated recurrent glioblastoma." (PMID 38571509, 2024). "Furthermore, lomeguatrib has been proposed as a potential radiosensitizer for glioblastoma cells with unmethylated MGMT." (PMID 39055560, 2024). "The methylation data obtained in this study were consistent with what has been reported in the literature regarding different types of high-grade gliomas since methylation of the MGMT promoter is found in 50% of glioblastomas, in 75% of astrocytomas, and in almost all oligodendrogliomas." (PMID 39767683, 2024). "The methylation status of the MGMT promoter in glioblastoma serves not only as a prognostic indicator of disease outcome but also as a predictive marker for the efficacy of treatment with alkylating agents, thereby informing clinical decision-making and personalized treatment strategies." (PMID 39055560, 2024). "The research has further provided consistent results suggesting the use of combination therapy or personalized therapy, viz., both CCNU/temozolomide for newly diagnosed glioblastoma patients with methylated MGMT promoter being superior to the use of single therapy." (PMID 37937301, 2023). "The role of MGMT gene expression in the treatment of glioblastoma has a major significance." (PMID 37937301, 2023). "However, the response of glioblastoma patients to temozolomide depends on the expression level of the repair protein O6-methylguanine-DNA methyltransferase (MGMT) in the tumor." (PMID 38136323, 2023).
glioblastoma (continued). "However, TMZ treatment often results in drug resistance in ~50% of glioblastoma patients due to overexpression of MGMT, which reverses the methylation of the O6 position of guanine." (PMID 38239396, 2023). "MGMT promoter was methylated in 36 patients (4 anaplastic oligodendroglioma, 5 anaplastic astrocytoma, and 27 glioblastoma), whereas in 1 glioblastoma, 2 anaplastic astrocytomas and 1 anaplastic oligodendroglioma we couldn’t determine the methylation status." (PMID 37341199, 2023). "Around half of glioblastomas exhibit promoter hypermethylation, leading to reduced levels of the dealkylating enzyme MGMT that specifically and directly removes alkylation lesions induced by TMZ and is, therefore, an established biomarker of TMZ effectiveness and short-term clinical response." (PMID 37777579, 2023). "Also, the GLARIUS trial cohort is restricted to MGMT promotor unmethylated glioblastoma while AVAglio included both MGMT-methylated and MGMT-unmethylated tumors." (PMID 37787906, 2023). "In the current retrospective study, we compared the MGMT-methylation pattern of isocitrate dehydrogenase (IDH)-wildtype glioblastomas from patients, who survived more than 3 years (long-term survivors) with those who survived less than 1 year (short-term survivors)." (PMID 37641156, 2023). "MGMT methylation levels were heterogenous across glioblastoma." (PMID 37665980, 2023). "Molecular markers of glioblastoma such as methylated O6-methylguanine-DNA methyltransferase (MGMT) promoter methylation was seen in 16 out of the 33 patients evaluated (48%) and expression of immunological markers such as TNF-a, IL-1β, and IL-6 was considered in one patient." (PMID 38137175, 2023). "Different results have been reported concerning the relationship of the apparent diffusion coefficient (ADC) values and the status of methylation as the promoter gene for the enzyme methylguanine-DNA methyltransferase (MGMT) in patients with glioblastomas (GBs)." (PMID 36900177, 2023). "In addition to upregulated MGMT expression, glioblastoma often exhibits enhanced DNA damage repair capacity through several related mechanisms." (PMID 38239396, 2023). "Similarly, epigenetics factors, such as CpG island methylation phenotype of O6-methylguanine-DNA methyltransferase (MGMT) promoter, are also commonly used for glioblastoma tumor stratification." (PMID 38239396, 2023). "MGMT methylation status is a useful marker in the prognosis of glioblastoma." (PMID 36768201, 2023). "Thus, in glioblastomas, where approximately 45% bear a methylated MGMT promoter, treatment with TMZ produces a survival advantage for these types of patients and is used as an oral alkylating agent to treat the disease." (PMID 36672401, 2023). "In addition, CheckMate-548 yielded similar negative results in a phase III trial which compared nivolumab plus standard chemoradiation versus standard chemoradiation in patients with MGMT-methylated glioblastoma." (PMID 36229714, 2023). "About 50% of glioblastoma patients have a methylated MGMT promoter region (MGMT-met)." (PMID 38168519, 2023). "Tumor PGBM underwent extensive histopathological and genomic analysis for clinical purposes and demonstrated diffuse and high-grade glioblastoma histology, IDH1 mutation (IDH1 c.395G>A [p.Arg132His]), MGMT promoter methylation profile, TERT promoter wild-type, and absence of 1p/19q codeletion." (PMID 37192626, 2023). "For MGMT promoter methylated glioblastomas, intensification of temozolomide chemotherapy by additional administration of CCNU might be beneficial." (PMID 38032426, 2023). "MGMT promoter methylation has been known as a predictive biomarker for the response to radiotherapy and a prognostic biomarker for adjuvant alkylating chemotherapy in patients with glioblastomas." (PMID 37835379, 2023). "In contrast, in MGMT promoter unmethylated glioblastoma, radiation was beneficial." (PMID 38032426, 2023).
glioblastoma (continued). "The response of glioblastoma (GBM) patients to the alkylating agent temozolomide (TMZ) vitally depends on the expression level of the repair protein O6-methylguanine-DNA methyltransferase (MGMT)." (PMID 38136323, 2023). "Furthermore, we compared iPSC-GBM with iPSC-derived sFRP4 overexpressed glioblastoma cells and found MGMT expression was downregulated in iPSC-derived sFRP4 overexpressed glioblastoma cells." (PMID 37509281, 2023). "Moreover, we recently reported that the HPLC method was a powerful tool in glioblastoma cases to evaluate the methylation status of the MGMT gene, which is a well-known biomarker to predict the clinical response to temozolomide in glioblastoma cases." (PMID 37839090, 2023). "Age, KPS, MGMT status, and various molecular genetic alterations are the primary prognostic factors that significantly influence the outcome of patients diagnosed with glioblastoma." (PMID 37881322, 2023). "Therefore, the treatment with TMZ is found to be very effective in brain tumors with methylated MGMT promoter, i.e. in the secondary glioblastoma, as it plays a critical factor for the efficacy of TMZ." (PMID 37937301, 2023). "For example, miR-370-3p inhibits chemotherapy resistance to glioblastoma by targeting MGMT." (PMID 36793374, 2023). "The different relationship of MGMT methylation with the efficacy of alkylating agents on glioblastoma and LMS could be related to the importance of molecular mechanisms in the two settings." (PMID 37371106, 2023). "And MGMT promoter methylation status is an independent favorable prognostic factor in glioblastoma." (PMID 37308741, 2023). "MGMT is a strong prognostic biomarker in patients with glioblastoma." (PMID 37026932, 2023). "We evaluate the treatment benefit of bevacizumab according to gene expression subtypes of pretreatment tumor samples (n = 123) in the GLARIUS trial (NCT00967330) for MGMT unmethylated glioblastoma patients with Kaplan-Meier analyses, log-rank tests and Cox regression models." (PMID 37787906, 2023). "The role of MGMT is most relevant in the management of glioblastoma." (PMID 33850305, 2022). "MGMT mediates a DNA repair mechanism, and epigenetic silencing through methylation of the MGMT promotor confers a positive prognosis and predicts response to temozolomide (an alkylating agent) in patients with glioblastoma." (PMID 35804940, 2022). "It is used for the detection of small DNA mutations (e.g., EGFR mutations), gene fusions (e.g., RNA-based testing for ALK), or DNA methylation analysis using methylation-specific PCR (e.g., MGMT promoter methylation in glioblastoma or Septin9 gene methylation in CRC)." (PMID 35892331, 2022). "MGMT promoter methylation percentage (MGMTpm%) obtained with pyrosequencing correlates with the tumor volume ratio (TVR) obtained with magnetic resonance imaging (MRI) in isocitrate dehydrogenase (IDH)-wildtype glioblastoma." (PMID 36291588, 2022). "MGMT methylation is clinically used for treatment decision in elderly glioblastoma patients." (PMID 36428772, 2022). "Methylation of the MGMT promoter is detected in 35–75 percent of glioblastomas." (PMID 36011048, 2022). "Our large study suggested that a threshold of 15% for MGMT might have a moderate discriminative performance regarding survival in glioblastoma patients." (PMID 35626029, 2022). "Previous studies showed that the coexistence of IDHmut and MGMTmet significantly prolonged the overall survival of glioblastoma patients who received temozolomide and radiation therapy, and IDH mutation and MGMT promoter methylation were independent predictive factors for pseudoprogression disease." (PMID 36711137, 2022). "Many studies have reported MGMT promoter methylation as a prognostic factor for glioblastoma." (PMID 35397757, 2022).
glioblastoma (continued). "Although the usefulness of MGMT promoter methylation analysis in glioblastoma patients for predicting the prognosis and response to chemoradiotherapy with temozolomide has been widely reported, there is still no consensus regarding how to measure MGMTpm% and how to define MGMTpm% cutoff values." (PMID 35397757, 2022). "All these studies show that MGMT methylation represents a good prognostic marker in glioblastoma." (PMID 35806478, 2022). "The inhibition of MGMT in glioblastoma cells treated with Ageritin showed a direct correlation between Ageritin treatment and DNA damage and the different inhibition times between the two cell lines NULU and ZAR, highlighting the heterogeneity of the response of the glioblastoma to chemotherapy." (PMID 35458581, 2022). "When compared with glioblastoma-37-on-a-chip, glioblastoma-28-on-a-chip was more susceptible to O6BG (a pseudosubstrate of MGMT) and MX (a base excision repair pathway inhibitor), including the combination of O6BG + MX and the combination of CIS + KU + O6BG + radiation." (PMID 35565282, 2022). "We conclude that diminished EFGR activity in the context of MGMT-null organisms, may underlie the acquisition of TMZ resistance and quiescence of CSCs in recurrently-treated glioblastoma." (PMID 36316307, 2022). "MGMT is one of the most widely studied markers in glioblastoma." (PMID 36551786, 2022). "In addition, EGFRvIII/Ki67 (20% or less) and EGFRvIII/methylated MGMT combinations positively impacted the prognosis of glioblastoma patients." (PMID 35806478, 2022). "Thus, MGMT promoter methylation status is a prognostic and a predictive marker for temozolomide in glioblastomas, and evaluation of MGMT promoter methylation is considered important for predicting treatment efficacy and prognosis." (PMID 35397757, 2022). "Obesity was associated with shorter survival in MGMT methylated, but not in MGMT unmethylated glioblastoma patients." (PMID 35704157, 2022). "We prospectively followed twenty-two consecutive Isocitrate Dehydrogenase (IDH) wild-type glioblastoma patients (6 O6-Methylguanine-DNA methyltransferase methylated (MGMTm); sixteen MGMT unmethylated (MGMTu)) who underwent maximal safe resection of recurrent tumor followed by GT placement." (PMID 35088050, 2022). "In older patients with primary glioblastoma, decreased exogenous methionine, coupled with decreased methylation of the MGMT promoter, could result in MGMT expression, increased repair of TMZ-alkylation damage, and decreased patient survival." (PMID 35806160, 2022). "Furthermore, promoter methylation status of the O6-methylguanine DNA methyltransferase (MGMT) is a prognostic indicator of the clinical response to treatment of glioblastoma patients with temozolomide (TMZ)." (PMID 35444654, 2022). "Notably, although not considered in this paper, the O6-methylguanine-DNA methyltransferase (MGMT) promoter methylation is also one of the most important biomarkers for glioblastomas." (PMID 35406550, 2022). "Pathology includes glioblastoma (3/3), methylguanine-DNA methyltransferase (MGMT) methylated (2/3), isocitrate dehydrogenase 1 (IDH1) mutant (0/3), epidermal growth factor receptor (EGFR) amplification (0/3), and α thalassemia/mental retardation syndrome X‐linked (ATRX) (3/3)." (PMID 36148206, 2022). "In a phase III study of MGMT methylated glioblastoma (CENTRIC EORTC 26,071–22,072 study), the short half-life of cilengitide was considered to be one of the reasons for failure, suggesting that it may have had an insufficient inhibitory effect on angiogenesis." (PMID 35713706, 2022). "Moreover, in the frontal lobe, localized in the left hemisphere, MGMT-methylated, IDH1-mutated glioblastomas appeared." (PMID 35330402, 2022). "MGMT-silenced, temozolomide-treated patients suffered recurrence after a longer time interval (14.9 versus 9.2 months, p = 0.02) and outside the radiation field, enforcing the role of MGMT gene methylation in glioblastoma prognosis." (PMID 35806153, 2022).
glioblastoma (continued). "Furthermore, the C1 and C2 cell line clusters do not appear to have any relationship to known characteristics of glioblastoma such as MGMT methylation status." (PMID 35406779, 2022). "Few studies have reported a correlation of promoter methylation at the methylguanine-DNA methyltransferase (MGMT) gene with favorable treatment outcomes in glioblastoma patients treated with temozolamide, suggesting its possibility to be used as an epigenetic biomarker." (PMID 36092905, 2022). "However, several studies showed that ADC values were significantly higher in glioblastomas with MGMT-m than with MGMT-um." (PMID 36471242, 2022). "In the treatment of relapsed MGMT promotor-methylated glioblastoma, standard chemotherapy may consist of TMZ or CCNU." (PMID 35045869, 2022). "This large multicenter study indicated that a threshold of 15% for MGMT might have a moderate discriminative performance regarding survival in IDH wild-type glioblastoma patients treated with radio-chemotherapy with temozolomide as first-line therapy." (PMID 35626029, 2022). "as VMs using DSP in 10 cases of MGMT methylated versus unmethylated IDH-wild-type glioblastoma." (PMID 35847846, 2022). "Besides, MGMT promoter methylation can predict responsiveness to alkylating chemotherapies in glioblastoma." (PMID 36003766, 2022). "Thus, MGMT provides a promising therapeutic target for over half of glioblastoma patients that have un-methylated MGMT." (PMID 33850305, 2022). "O6-Methylguanine–DNA Methyltransferase (MGMT) is a key protein in the DNA repair mechanism of damages induced by alkylating agents and, as illustrated in glioblastoma, the epigenetic silencing of MGMT is a mechanism that potentiates the effect of Temozolomide (TMZ)." (PMID 35565369, 2022). "Furthermore, MGMT silencing by promoter methylation in adult glioblastoma is a predictive biomarker for benefit from alkylating agent chemotherapy." (PMID 35338570, 2022). "Although the positive predictive value of MGMT promoter methylation in glioblastoma patients is widely acknowledged, the prognostic value remains unclear or controversial." (PMID 36009577, 2022). "Taken together, the addition of BET-inhibitors to the current standard of care, comprising temozolomide treatment, may sensitize the 50% of patients whose glioblastoma exert an unmethylated MGMT promoter." (PMID 36513631, 2022). "Pyrosequencing is the gold standard test for MGMT promoter methylation in glioblastoma." (PMID 36291588, 2022). "It is established that the MGMT promoter methylation affects the TMZ-response of glioblastoma." (PMID 35563629, 2022). "Thus, the MGMT promoter methylation status is a prognostic and predictive marker for temozolomide in glioblastomas, and its evaluation helps predict the treatment efficacy and prognosis." (PMID 36291588, 2022). "The prognostic impact of obesity in MGMT methylated glioblastoma was confirmed in a multivariable Cox regression (adjusted odds ratio: 2.57 (95% CI 1.53–4.31), p < 0.001) adjusted for age, sex, extent of resection, baseline steroids, Karnofsky performance score, and treatment arm." (PMID 35704157, 2022). "However, mostly because of its simplicity and low cost, MSP is still the best method for MGMT methylation assessment in glioblastomas." (PMID 35806153, 2022). "Our patient’s survival of more than three years is more than the median overall survival of patients with glioblastoma and methylated MGMT promotor with standard therapy, ranging from 21.7 up to more than 30 months, mostly due to a better response to alkylating chemotherapy." (PMID 35448029, 2022). "The assay used for MGMT analysis is an in house developed validated assay for glioblastoma samples." (PMID 35677534, 2022). "Overall, Ageritin could be considered as a possible innovative glioblastoma treatment, directly damaging DNA and downregulating the MGMT DNA repair protein." (PMID 35458581, 2022).